GLUD1 (glutamate dehydrogenase 1)
Diseases named in the same sentence as GLUD1 in open-access papers (continued):
Sharing a sentence is not in itself a finding about the gene and the disease.
cancer (continued). "Whereas most cancer cells use glutamate dehydrogenase (GLUD1) to convert glutamine-derived glutamate into α-ketoglutarate to refill mitochondrial carbon pool, PDAC use glutamine-derived aspartate to maintain the cellular redox state." (PMID 32756381, 2020). "Apart from conversion of glutamate to α-ketoglutarate using glutamate dehydrogenase 1 (GLUD1), cancer cells utilize glutamic-oxaloacetic transaminase 1 (GOT1) to generate oxaloacetate from glutamine-derived aspartate." (PMID 32370075, 2020). "The inhibition of GLUD1 decreases fumarate levels, which leads to decreased glutathione peroxidase activity, resulting in reduced scavenging of ROS, thereby attenuating cancer proliferation." (PMID 30634602, 2019). "In summary, our findings revealed that SIRT5 is a regulator of cancer glutaminolysis via its activation of GLUD1 in a deglutarylation-dependent manner, suggesting SIRT5 as a promising anti-CRC target for the selective killing of cancer cells." (PMID 29416026, 2018). "Suppression of GLUD1 activity leads to decreased fumarate levels and GPx activity, elevation of ROS and attenuation of cancer cell proliferation and tumor growth." (PMID 29272308, 2017). "Mitochondrial glutamate dehydrogenase GLUD1 controls redox homeostasis in cancer cells via the product of its activity, α-ketoglutarate, and its metabolite, fumarate." (PMID 29272308, 2017). "Cancer cells enhance glutaminolysis via positive regulation of GLUD1 to respond to increased demand of glutamine, which is used as a carbon source for energy generation, a component of protein and nucleotide, and in production of glutathione and NADPH." (PMID 27924922, 2016). "Recent studies demonstrated that glutamate dehydrogenase 1 controls the intracellular level of α-ketoglutarate, which is important for maintaining redox homeostasis in cancer cells." (PMID 26799418, 2016). "Glutamate dehydrogenase 1 (GLUD1) exhibits dichotomous effects across different cancer types." (PMID 40710547, 2025). "The results revealed that the gene methylation of GLUD1 in pan-cancer." (PMID 38245763, 2024). "Indeed, GLUD1 is overexpressed in various cancer cells, promoting epithelial-mesenchymal transition and drug resistance." (PMID 37009798, 2023). "During anaplerosis, mitochondrial glutamate dehydrogenase 1 (GLUD1) plays a key role by catalyzing the conversion of glutamate to alpha-ketoglutarate (α-KG) and releasing ammonia, which regulates autophagy and neutralizes the intracellular pH in cancer cells." (PMID 37009798, 2023). "In addition, two specific GLUD1 inhibitors (purpurin and a purpurin analogue, R162) are potent inhibitors in cancer cells." (PMID 35008989, 2022). "However, in cancers, the α-KG formation has received increased attention, emphasizing the role of GLUD1 in α-KG synthesis." (PMID 35847357, 2022). "GLUD1 has been proved to be a mitochondrial matrix enzyme in glutaminolysis and contributes to the control of autophagy to regulate the malignant phenotype of cancer cells." (PMID 35595754, 2022). "Taking into consideration that GLUD1 gene silencing leads to the apoptosis of HepG2 cells, we wondered if the activation mechanism was the intrinsic pathway since it is the most frequently deregulated type of cell death in cancers." (PMID 34829892, 2021). "Moreover, by using Genevisible database, it has been possible to perform a comparison between GLUD1 gene expression in normal and cancer livers." (PMID 34829892, 2021). "In addition, the mammalian target of rapamycin complex 1 the activity of which is dysregulated in many cancers, activates GLUD1 via inhibition of SIRT428." (PMID 27924922, 2016). "Most cancers depend on GLUD1-mediated glutamine metabolism to fuel the TCA cycle." (PMID 26439804, 2015). "Any factors that affect the GLUD1 expression and activity may interfere with cancer cell survival." (PMID 36207479, 2023).
cancer (continued). "Inhibition of glutamate dehydrogenase 1 (GLUD1), an enzyme localized in the mitochondrial matrix that is responsible for the conversion of glutamate to αKG and ammonia, leads to the attenuation of cancer cell proliferation and tumor growth by promoting imbalances in redox homeostasis." (PMID 36185202, 2022). "In parallel, growing evidence shows that cancer cells hijack these same mitochondrial programs to fuel anabolic growth and redox balance, often through rewiring of enzymes such as GLS2, GLUD1, or CPS1." (PMID 40710547, 2025). "Glutaminolysis is essential for the proliferation of cancer cells, thus inhibiting glutamine transporter SLC1A5 with almonertinib and/or V9302, and downregulating GLUD1 with OSC is a potential therapeutic approach for NSCLC." (PMID 38841622, 2024). "The GLUD isoenzymes GLUD1 and GLUD2 are both increased in human malignancies, allowing cancer cells to employ this pathway for growth and proliferation." (PMID 37048450, 2023). "Our data demonstrated that after sevoflurane administration, the MPC1 and GLUD1 expressions were upregulated, enhancing the activity of the TCA cycle to meet the demands of cancer survival and progression." (PMID 36207479, 2023). "Alternatively, the corresponding transporters and enzymes have been found to be highly expressed in these cancer patient samples, such as SLC1A5, GLS, and GLUD1." (PMID 36077501, 2022). "We also showed that GLUD1 is critical and sufficient for SIRT5-mediated cancer progression, both in vivo and in vitro." (PMID 29416026, 2018). "Consistently, our in vitro and in vivo results showed that GLUD1, an enzyme involved in glutaminolysis, is critical for SIRT5-driven cancer progression." (PMID 29416026, 2018). "Inhibiting GLUD1/RSK2 has been shown to enhance the infiltration of CD8 + T cells and increase IFN-γ levels within tumors, indicating the critical role of GLUD1 in shaping the immune microenvironment in specific cancer subtypes." (PMID 38459595, 2024). "Therefore, we selected proteins that were significantly lower expressed in cancer both in the CPTAC Discovery study and the Chinese-LUAD study, and found that two of the predicted substrates, namely ZBTB20 and GLUD1, were lower in cancer." (PMID 39125654, 2024). "Glutamate is produced in mitochondria from glutamine, which is catalyzed by glutaminase (GLS), which is then converted into α-KG by glutamate dehydrogenase 1 (GDH1), fueling the TCA cycle and contributing to biosynthesis, energy generation and the cellular homeostasis of cancer cells." (PMID 39330272, 2024). "The glutamate can be converted to α-ketoglutarate under the activation of GLUD1 and used by the TCA cycle to restore the survival of cancer cells as the intermediates of the TCA cycle are the source for the synthesis of amino acids, proteins, fatty acids, lipids, carbon skeleton, and nucleic acids." (PMID 36207479, 2023). "The conversion of glutamine to glutamate by glutaminase (GLS1 or GLS2), which is further transformed to α-ketoglutarate (α-KG) by glutamate dehydrogenase (GLUD1 or GLUD2) or aminotransferases, promotes the TCA metabolism that contributes to sustaining the energy used for cancer cell proliferation." (PMID 35054324, 2022). "In this study, we demonstrate that human GLUD1 gene silencing in HCC cells reduces HepG2 cell proliferation, while it has an opposite effect in normal hepatocytes as well as previously demonstrated in other cancer cells." (PMID 34829892, 2021). "Additionally, the conversion of glutamate to α-KG catalyzed by GLUD1 is also coupled with NADPH production, which is required for redox control and cancer cell proliferation." (PMID 29416026, 2018). "The metabolism of glutamate into α-ketoglutarate is catalyzed by glutamate dehydrogenase 1 (GDH1), glutamate pyruvate transaminase 2 (GPT2), or glutamate oxaloacetate transaminase 1 and 2 (GOT1 (cytoplasmic) and GOT2 (mitochondrial)), which were al previously reported to be overexpressed in cancer." (PMID 35158820, 2022).
cancer (continued). "Recent study suggests that glutamate dehydrogenase 1 (GDH1), a mitochondrial enzyme critical for redox homeostasis, is shown to control the intracellular levels of α-ketoglutarate and further metabolite fumarate, which binds to and activate GPx1 in cancer cells." (PMID 27023612, 2016). "Genes involved in the glutamine-dependent transamination pathway (GLS1, GOT1/2, ME1) and NQO1, but not GLUD1, are highly expressed in PDA relative to other cancers." (PMID 26462257, 2015). "In contrast, GLUD1, which diverts glutamine carbon away from the GOT2–GOT1–ME1 pathway into an alternate metabolic pathway, was not upregulated in PDA relative to other cancer types." (PMID 26462257, 2015).
tumor (72 papers, 2011 to 2026). "Positive associations with several glutamine metabolic enzymes were also detected, among these, GLS2 and glutamate dehydrogenase (GLUD1) which are associated with tumours of good prognosis and favourable patient outcome." (PMID 32200487, 2020). "Tumor expression of GLUD1 was associated with larger tumor size, while tumor expression of GOT1 was significantly linked with tumor dedifferentiation, vascular invasion, and lymphatic invasion." (PMID 25719198, 2015). "In this work, based on various cohorts, we assessed the correlations between GLUD1 with IL-32 gene expression levels in HCC tissues, between SYVN1 and LASP1 gene expression levels in HCC tissues, and between GLUD1 gene expression level and tumor size in HBV-associated HCC." (PMID 38587834, 2024). "GLUD1 level was negatively associated with the tumor immunosuppressive microenvironment (TIME)." (PMID 36203437, 2022). "Notably, high GLUD1 expression combined with low SLC25A13 expression had a higher association with tumor aggressiveness than did individual expression of each." (PMID 27924922, 2016). "Tumor expression of GLUD1 was associated with larger tumor size (P = 0.0086)." (PMID 25719198, 2015). "GPX1 can also mediate redox homeostasis and tumor progression, which are regulated by glutamate dehydrogenase 1 (GDH1)." (PMID 40346054, 2025). "Studies have shown that drug resistant tumor cells are highly dependent on Gln utilization, with glutamate dehydrogenase 1 (GLUD1) serving as a key factor in Gln addiction in acquired drug-resistant NSCLC cells." (PMID 40276500, 2025). "For instance, the expression of glutamate dehydrogenase 1 (GDH1) is upregulated in circulating tumor cells (CTCs), which contributes to anti-anoikis signals and promotes metastatic behavior in liver kinase B1 (LKB1)-deficient lung cancer." (PMID 41390768, 2025). "The HA-labeled GLUD1 expression plasmid was constructed and transfected into the tumor cell lines HepG2 and Huh7." (PMID 38587834, 2024). "Reports showed that dysregulation of both the expression level and activity of GLUD1 affected α-KG generation, and then regulated tumor cells proliferation and metastasis through affecting cellular metabolism." (PMID 38216781, 2024). "The results showed that the expression of GLUD1 in normal tissues was significantly higher than tumor tissues in unpaired samples, while the expression of GLUD1 in 72 paired samples showed the same results." (PMID 38245763, 2024). "GLUD1 overexpression significantly inhibited HCC cells proliferation, migration, invasion and tumor growth both in vitro and in vivo, while GLUD1 knocking-down promoted HCC progression." (PMID 38216781, 2024). "Taken together, these results showed that GLUD1 was down-regulated in tumor tissues, and the high expression level of GLUD1 indicated good prognosis for HCC patients." (PMID 38216781, 2024). "The tumor xenograft assay in nude mice determined the effect of GLUD1 overexpression on the suppression of HCC cell proliferation in vivo." (PMID 38587834, 2024). "In conclusion, our study demonstrates that GLUD1 is down-regulated in tumor tissues of HCC patients and inhibits HCC progression both in vitro and in vivo." (PMID 38216781, 2024). "Both the mRNA and protein expression levels of GLUD1 were reduced in HCC tumor tissues compared to the normal liver tissues." (PMID 38216781, 2024). "The results showed that GLUD1 mRNA expression was reduced in tumor tissues and correlated with the progression of ccRCC." (PMID 38245763, 2024). "Taken together, these results prove that GLUD1 is a tumor-suppressor and down-regulation of GLUD1 promoted HCC proliferation and metastasis both in vitro and in vivo." (PMID 38216781, 2024). "Based on MEXPRESS database, we found that the methylation levels of GLUD1 promoter in ccRCC tissues were significantly upregulated as neoplasm histologic grade progressed and positively correlated with lymph node metastasis." (PMID 36203437, 2022).
tumor (continued). "Only for advance NSCLC, high vs. low tumour folate was significantly associated with the overexpression of MCT1, MCT4, LDHA, SLC7A5, SIRT3, and GLUD1." (PMID 36615660, 2022). "Glutamate dehydrogenase 1 (GDH1) transmits its signals through antioxidant glutathione peroxidase 1 (GPx-1) to regulate redox homeostasis, malignant cell proliferation and tumor growth." (PMID 35773307, 2022). "Together, we found a novel tumor-suppressing role of GLUD1 in ccRCC which was different from that in other tumors and a new mechanism for inhibiting PI3K/Akt/mTOR activation and TIME in ccRCC." (PMID 36203437, 2022). "Although in vitro cell cultures and tumor samples are clearly different, we have explored if high GLUD1 expression observed in hPheo1 cells are also expressed in human PCCs/PGLs (TCGA data)." (PMID 35008989, 2022). "The analysis of GLUD1 mRNA expression levels in cell lines highlights the significantly higher expression of this gene in HepG2 cells than in the other tumor cell lines." (PMID 34829892, 2021). "Among these is GLUD1, which was weakly associated with GLS and GLS2 at both mRNA and protein levels in the low and high proliferative tumours." (PMID 34439127, 2021). "CyTOF analysis showed that CD8+PD-1+ cells in tumor had decreased expression of ATP5a, cytochrome c, and GLUD1, suggesting that these T cells decreased utilization of the electron transport chain for energy production." (PMID 32814710, 2020). "Here we identified five lysine acetylation sites in GLUD1, and all the acetylation levels were down-regulated in tumor tissues." (PMID 33093847, 2020). "Remarkably, the xenograft study showed delayed tumor growth, as well as decreased tumor size and mass, when GLUD1 was inhibited in SIRT5-overexpressing tumors, which suggested that GLUD1 knockdown abolished SIRT5-induced tumor growth significantly in vivo." (PMID 29416026, 2018). "Tumor growth was evaluated and at the end of the experiment, tissue sections taken from the xenografts were subjected to GLUD1 enzyme activity analysis." (PMID 29416026, 2018). "We found that overexpression of SIRT5 promotes glutamine anabolic metabolism by activating GLUD1 in a deglutarylation-dependent manner, and is associated with CRC cell proliferation, survival, and xenograft tumor growth." (PMID 29416026, 2018). "Clinical PDA cases expressing a high GOT1 to GLUD1 or GOT2 to GLUD1 ratio in the tumor have worse outcomes." (PMID 26462257, 2015). "To validate it, we sought to determine whether inhibiting GCLC (M27) or GLUD1 (M28) increases MHC‐I antigen presentation in tumor cells." (PMID 39482885, 2025). "In addition, GLUD1-induced suppression of cell proliferation and migration was demonstrated in GLUD1-overexpressing HepG2 and Huh7 cells and tumor xenografts in nude mice." (PMID 38587834, 2024). "In this study, we confirmed down-regulation of GLUD1 in tumor samples from HCC patients." (PMID 38216781, 2024). "To date, whether GLUD1 silencing triggers the transformation of normal hepatocytes to tumor cells is still unknown, and further studies on this issue are required." (PMID 38587834, 2024). "In this study, we analyzed clinical information and GLUD1 expression obtained from the TCGA database of ccRCC, results showed that GLUD1 expression was reduced in the tumor tissues and correlated with the malignancy of ccRCC, high expression of GLUD1 predicted a better prognosis for ccRCC patients." (PMID 38245763, 2024). "We therefore assessed the correlation of GLUD1 expression with tumor immune microenvironment." (PMID 36203437, 2022). "Expressions of four transcripts including L-type amino acid transporter 1 (SLC7A5), the high-affinity L-glutamine transporter (SLC1A5), glutaminase (GLS), and glutamate dehydrogenase 1 (GLUD1) were all significantly up regulated in T3 as compared with T1 and T2 tumours." (PMID 36615660, 2022).